LINC01567 (long independently transcribed non-coding RNA 1567)
Synonyms: LOCCS
Gene: Long non-coding RNA gene on chromosome 16 (24,661,422 to 24,671,062, reverse strand). Ensembl gene ENSG00000224310.
Diseases named in the same sentence as LINC01567 in open-access papers:
LINC01567 is named in the same sentence as 2 diseases in open-access papers, as found by Europe PMC text mining. Sharing a sentence is not in itself a finding about the gene and the disease. The quoted sentences say what the papers report.
colon cancer (1 paper, 2017). "In previous studies, we found the expression of a lncRNA (ENST00000414816, also referred to as long intergenic non-protein-coding RNA 1567; LINC01567) was significantly upregulated in colon cancer–derived spheroid cells (data not published)." (PMID 29110645, 2017).
tumor (2 papers, 2017 to 2020). "LINC01567 (also known as LOCCS) is highly expressed in colon CSCs that express CD133+/CD166+/CD44+, and its inhibition suppresses the proliferation, migration, invasion and tumor xenografts of colon CSCs via sponging miR-93." (PMID 33246471, 2020).